TOP1 (DNA topoisomerase I)
Description:
Releases the supercoiling and torsional tension of DNA introduced during the DNA replication and transcription by transiently cleaving and rejoining one strand of the DNA duplex. Introduces a single-strand break via transesterification at a target site in duplex DNA. The scissile phosphodiester is attacked by the catalytic tyrosine of the enzyme, resulting in the formation of a DNA-(3'-phosphotyrosyl)- enzyme intermediate and the expulsion of a 5'-OH DNA strand. The free DNA strand then rotates around the intact phosphodiester bond on the opposing strand, thus removing DNA supercoils. Finally, in the religation step, the DNA 5'-OH attacks the covalent intermediate to expel the active-site tyrosine and restore the DNA phosphodiester backbone (By similarity). Regulates the alternative splicing of tissue factor (F3) pre-mRNA in endothelial cells. Involved in the circadian transcription of the core circadian clock component BMAL1 by altering the chromatin structure around the ROR response elements (ROREs) on the BMAL1 promoter.
Synonyms: TOPI
Tractability: Small molecule: an approved drug acts on it; a structure with a bound ligand is known; a high-quality ligand is known; it has a high-quality binding pocket; it belongs to a druggable protein family. PROTAC: UniProt records ubiquitination sites on it; ubiquitination databases record sites on it; its protein half-life has been measured; a small molecule that binds it is known. Other modalities: an approved drug acts on it.
Target class: Isomerase; Enzyme
Chemical probes: EDOTECARIN, PD080783, PD081356, PD081478, PD081719, PD081766, PD082351, PD082395, PD082415, PD082652, PD082819, PD082871, PD083025, PD083027, PD083356, PD083564, PD083919, PD084113, PD084436, PD084572, and 3 more
Safety:
Unwanted effects reported when the protein is acted on. In parentheses: how it was acted on, where the effect was seen, and who reports it.
Neutropenia (source: ClinPGx)
Gene: Protein-coding gene on chromosome 20 (41,028,822 to 41,124,487, forward strand). Ensembl gene ENSG00000198900.
Subcellular location: Nucleus, nucleolus; Nucleus, nucleoplasm
Subcellular location (Human Protein Atlas): Nucleoli fibrillar center; Nucleoplasm
Pathways (Reactome):
Metabolism of proteins: SUMOylation of DNA replication proteins
Gene Ontology:
Molecular function: ATP binding; chromatin binding; DNA binding; DNA binding, bending; DNA topoisomerase type I (single strand cut, ATP-independent) activity; double-stranded DNA binding; molecular condensate scaffold activity; protein binding; protein domain specific binding; protein serine/threonine kinase activity; RNA binding; RNA polymerase II cis-regulatory region sequence-specific DNA binding; single-stranded DNA binding; supercoiled DNA binding; chromatin DNA binding; protein-containing complex binding
Biological process: chromatin remodeling; circadian regulation of gene expression; circadian rhythm; DNA topological change; response to xenobiotic stimulus; chromosome segregation; DNA replication; programmed cell death; animal organ regeneration; cellular response to luteinizing hormone stimulus; response to cAMP; response to gamma radiation; response to temperature stimulus; rRNA transcription
Cellular component: cytoplasmic ribonucleoprotein granule; fibrillar center; nuclear chromosome; nucleolus; nucleoplasm; nucleus; protein-DNA complex; chromosome; cytoplasm; dense fibrillar component; perikaryon
Genetic constraint (gnomAD): Loss-of-function variants: 4 observed, 75 expected, observed/expected ratio (o/e) 0.0533, 90% interval 0.025 to 0.12. The upper end of that interval is the gene's LOEUF score, 0.12, which puts it in group 1 of 6, group 1 being the genes least tolerant of losing a copy. Missense variants: 324 observed, 717.41 expected, observed/expected ratio (o/e) 0.45, 90% interval 0.41 to 0.5. Synonymous variants: 202 observed, 239.75 expected, observed/expected ratio (o/e) 0.84, 90% interval 0.75 to 0.95.
Cancer hallmarks: genome instability and mutations (suppresses); genome instability and mutations (promotes); escaping programmed cell death (promotes); escaping immune response to cancer; suppression of growth (promotes); cell replicative immortality; escaping programmed cell death; proliferative signalling (promotes)
Homologues: Orthologues: chimpanzee TOP1 (100% identical), macaque TOP1 (99% identical), dog TOP1 (98% identical), guinea pig TOP1 (98% identical), rabbit TOP1 (97% identical), mouse Top1 (97% identical), rat Top1 (97% identical), tropical clawed frog top1 (83% identical), zebrafish top1a (82% identical), zebrafish top1b (62% identical). Paralogues in human: TOP1MT (52% identical).
Diseases named in the same sentence as TOP1 in open-access papers:
TOP1 is named in the same sentence as 135 diseases in open-access papers, as found by Europe PMC text mining. Sharing a sentence is not in itself a finding about the gene and the disease. The quoted sentences say what the papers report.
breast carcinoma (37 papers, 2009 to 2025). "The desirability of targeting S-phase as a mode of action of breast cancer therapeutics is underlined by the topoisomerase I (TOP1) inhibitor irinotecan, which is a clinically effective pharmaceutical for advanced and metastatic breast cancer." (PMID 32817625, 2020). "Nevertheless, taken together, the data provides evidence that high Top1 mRNA expression is associated with aggressive breast cancers." (PMID 26959889, 2016). "Two proteins highly abundant in the BRCA1-deficient secretome, namely CDH3 and TOP1, were selected for validation in tumor tissue samples of breast cancer patients." (PMID 27566577, 2016). "Among them were several nuclear proteins, which have previously been identified in BRCA1-deficient breast carcinomas (TOP1, SMC3, SSRP1 and DHX9)." (PMID 27566577, 2016). "TOP1 expression was independently associated with BRCA1/2-related breast carcinomas (adjusted odds ratio [OR] 3.75; 95% confidence interval [95% CI], 1.82–7.71, p < 0.001)." (PMID 27566577, 2016). "We observed that Top1 mRNA overexpression was associated with aggressive highly proliferative breast cancers." (PMID 26959889, 2016). "A proteomic study using mouse Brca1-deficient mammary tumours has recently reported TOP1 as up-regulated therefore strengthening our findings." (PMID 23805307, 2013). "In this regard, TOP1 has been described as a prominent target in BRCA1-deficient breast cancer." (PMID 27566577, 2016). "Taken together, intracellular (nuclear) proteins of BRCA1-deficient breast tumor cells (e.g. TOP1) released through exosome-like EVs may represent putative candidates related to BRCA1-deficient breast cancer." (PMID 27566577, 2016). "TOP1 higher expression was shown to be associated with breast cancer, where it is a predictor of poor prognosis, but its role in colon cancer has not been established Antibody neutralization of TNFRSF6B in hepatocellular carcinoma cell lines inhibited proliferation and induced apoptosis." (PMID 22879877, 2012). "To test this, we performed Cleavage Under Targets and Release Using Nuclease (CUT&RUN) followed by next-generation sequencing (NGS) for macroH2A1.1 and TOP1 in MDA-MB-231 breast cancer cells, which express relatively high levels of macroH2A1.124." (PMID 40796804, 2025). "Impaired macroH2A1.1 splicing, a frequent cancer feature, was predictive of increased sensitivity to TOP1 poisons in a pharmaco-genomic screen in breast cancer cells, and macroH2A1.1 inactivation mirrored this effect." (PMID 40796804, 2025). "We also observed significantly elevated TOP1 protein expression in other cancers, including breast cancer, ovarian cancer, lung adenocarcinoma, and colon cancer." (PMID 35349486, 2022). "Topoisomerase I (TOP1) inhibitors cause DNA damage, making these drugs desirable for TNBC treatment since DNA repair machinery is defective in this subtype of breast cancer." (PMID 35844787, 2022). "Breast cancer cell lines selected for resistance following exposure to irinotecan have been found to have TOP1 with altered isoelectric points, consistent with altered PTMs of TOP1." (PMID 31547492, 2019). "Factor 12 also predicts insensitivity to TOP1-poisons and includes the canonical oncogenes such as ERBB2, TGFB3, ESR1 (AR), and FGFR4 that are strongly associated with breast cancer." (PMID 31695042, 2019). "Previously, we have shown that approximately 30% of patients with breast cancer are amplified for the TOP1 gene." (PMID 31196001, 2019). "Future randomized trials are warranted to identify the best chemotherapeutic options for metastatic breast cancer patients with increased TOP1 gene copy numbers." (PMID 31196001, 2019). "This is in contrast to results obtained from cell lines originating from tumors other than breast cancer, which demonstrated a direct correlation between TOP1 gene copy number and IC50." (PMID 31783818, 2019).
breast carcinoma (continued). "Multiple logistic regression was performed to estimate the predictive effects of TOP1 or CDH3 for BRCA1/2-related breast carcinomas when adjusted for triple negative breast cancer and age." (PMID 27566577, 2016). "In the METABRIC (Molecular Taxonomy of Breast Cancer International Consortium) cohort comprising 1977 breast cancers, ~20% of tumors were found to express high Top1 mRNA and ~83% were found to express high WRN mRNA." (PMID 26959889, 2016). "Further we analyzed the expression profiles of WRN and Top1 in a large cohort of human breast cancers to identify any correlations between gene expression and breast cancer specific survival." (PMID 26959889, 2016). "Protein expression of CDH3 and TOP1 was analysed in a panel of 253 human breast carcinomas comprising 102 BRCA1-related, 49 BRCA2-related and 102 sporadic breast carcinomas." (PMID 27566577, 2016). "In a panel of breast cancer cell lines with varying levels of TOP1 CN, TOP1 mRNA, Top1 protein and enzyme activity, we found consistency between the TOP1 CN and protein levels." (PMID 26801902, 2016). "Given the potential promise of Top1 inhibitors in breast cancer, the development of predictive biomarkers to personalize therapy is highly desirable." (PMID 26959889, 2016). "These preclinical observations should be clinically validated in breast cancer biopsies derived from clinical studies in which the patients were exposed to Top1 inhibitor treatment to generate level 1 evidence for use of these markers." (PMID 26801902, 2016). "Comparison between BRCA1-related and sporadic breast carcinomas demonstrated a significant difference in TOP1 expression (p = 0.002)." (PMID 27566577, 2016). "Top1 gene amplification has been reported in about 30% of breast cancers and a tight correlation between mRNA and protein expression was observed in the NCI-60 panel of cell lines." (PMID 26959889, 2016). "When TOP1 and CDH3 were combined, there was a significant association between breast carcinomas with positive TOP1 and CDH3 and BRCA1/2 mutations (adjusted OR 5.05; 95% CI, 1.75–14.6, p = 0.003)." (PMID 27566577, 2016). "In the present study, TOP1 was detected at an increased level in the BRCA1-deficient secretome and exosome-like vesicles as well as in human BRCA1-related breast carcinomas." (PMID 27566577, 2016). "Altered Top1 and WRN expression was not only associated with aggressive breast cancers but also correlated with adverse prognostic outcome in patients." (PMID 26959889, 2016). "Given the essential role of WRN and Top1 in DNA repair and replication we studied their role in breast cancer pathogenesis and prognosis." (PMID 26959889, 2016). "In particular, up-regulation of the BCRP drug efflux pump, low proliferation rates and down-regulation of Top1 protein are suggested as key mediators of SN-38 resistance in human breast cancer cell lines." (PMID 26801902, 2016). "Lately there has been an interest in using Top1 inhibitors in the treatment of breast cancer, which traditionally has been treated with other approaches." (PMID 26959889, 2016). "Increased levels in TOP1 and CDH3 were validated in a large population-based series of breast cancer patients with a BRCA1/2 mutation." (PMID 27566577, 2016). "In metastatic breast cancer (mBC) the Top1 protein expression has been evaluated by IHC in FFPE tissue from 22 primary breast cancer." (PMID 24400218, 2013). "By FISH analyses we have established the normal range of TOP1 copy numbers and found that 31% of primary breast cancer patients have TOP1 copy number gains (≥4 copies)." (PMID 24400218, 2013). "EGF induces nucleolar translocation of HPSE and induction of DNA topoisomerase I which is essential for BM from breast cancer and cell proliferation." (PMID 22567347, 2011). "Furthermore, our studies of two clinical cohorts find that SYCP2 overexpression correlates with breast cancer resistance to antibody-conjugated TOP1 inhibitor and ovarian cancer resistance to platinum treatment." (PMID 38383600, 2024).
breast carcinoma (continued). "We demonstrate that TOP1 and CDH3 are closely associated to BRCA1-deficient breast cancer." (PMID 27566577, 2016). "Therefore, we here applied immunohistochemistry for verification of increased expression of TOP1 and CDH3 in BRCA1-deficient breast carcinomas." (PMID 27566577, 2016). "Taken together, the pre-clinical data show that WRN and/or Top1 expression could have prognostic and/or predictive significance in breast cancers." (PMID 26959889, 2016). "Therefore we investigated the mRNA levels of WRN and Top1 in the METABRIC (Molecular Taxonomy of Breast Cancer International Consortium) cohort." (PMID 26959889, 2016). "However, a prospective clinical trial of Top1 inhibitor therapy in ER positive breast cancers would be required to confirm our in vitro results." (PMID 26959889, 2016). "To explore this hypothesis, we conducted the first large study of WRN and Top1 expression in human breast cancers." (PMID 26959889, 2016). "With the aims to search for Top1 inhibitor predictive molecular biomarkers and to identify which drugs are effective in irinotecan resistant BC cells, we have established human breast cancer cell line model systems for resistance to SN-38, the active metabolite of irinotecan." (PMID 26801902, 2016). "Interestingly, in patients with estrogen receptor (ER)-positive breast cancers, high WRN and high Top1 levels were associated with a bad prognosis." (PMID 26959889, 2016). "Additionally we show that in human breast cancers, Top1 and/or WRN expression has prognostic and predictive significance." (PMID 26959889, 2016). "Top1/WRN expression based stratification could be a promising approach to personalize Top1 inhibitor therapy in breast cancer patients." (PMID 26959889, 2016). "We report that TOP1 and CDH3 were expressed to a higher extent in BRCA1-related breast carcinomas relative to sporadic breast carcinomas, highlighting their potential clinical usefulness for breast cancer detection in women with a BRCA1 mutation." (PMID 27566577, 2016). "Therefore, we have used a TOP1/CEN-20 FISH probe mix to determine the TOP1 gene aberration frequency in clinical breast cancer biopsies (n = 100) and compared to findings in normal breast tissue (n = 100)." (PMID 24400218, 2013). "This association was independent of the presence of TNBC and age suggesting that assessment of TOP1 may substantially improve prediction of BRCA1/2 mutations, in particular in breast carcinomas with hormone-receptor positive or HER2 positive breast cancer diagnosed in women aged ≥ 45 years." (PMID 27566577, 2016). "As a novel ADC drug coupled with a TOP1 inhibitor, T-DXd is indicated for the treatment of adult patients with unresectable or metastatic HER2-low breast cancer who have received prior anti-HER2 therapies." (PMID 39697330, 2024). "Another study showed that aAbs to human DNA topoisomerase I were biomarkers for favorable prognosis in breast cancer, and this antibody induced ADCC in the in vitro studies with ER+ and triple-negative human breast cancer cell lines." (PMID 34360795, 2021). "For example, CPT effectively inhibits Top1 expression in the CPT-resistant breast cancer cell line BT474, while CPT is unable to inhibit Top1 expression in the CPT-sensitive breast cancer cell line ZR75–1." (PMID 33217967, 2020). "TOP1 overexpression was mostly observed in BRCA1-related (60%) and in BRCA2-related breast carcinomas (59%) as compared to sporadic breast carcinomas (35%)." (PMID 27566577, 2016). "We showed that expression of TOP1 and CDH3 was significantly increased in human BRCA1-related breast carcinomas relative to sporadic cases (p = 0.002 and p < 0.001, respectively)." (PMID 27566577, 2016). "To investigate WRN and Top1 expression and the phenomenon of CPT-induced WRN degradation in breast cancer cells, we used three CPT-sensitive (MCF-7, T47D and ZR-75-1) and three CPT-resistant (BT549, MDA-MB-231 and BT-474) cell lines." (PMID 26959889, 2016).